MAN1A1 (mannosidase alpha class 1A member 1)
Description:
Involved in the maturation of Asn-linked oligosaccharides. Progressively trim alpha-1,2-linked mannose residues from Man(9)GlcNAc(2) to produce Man(5)GlcNAc(2).
Synonyms: HUMM3; HUMM9; MAN9
Tractability: Antibody: UniProt predicts a signal peptide or a membrane-spanning region. PROTAC: ubiquitination databases record sites on it; its protein half-life has been measured.
Target class: Enzyme; Hydrolase
Gene: Protein-coding gene on chromosome 6 (119,177,204 to 119,349,767, reverse strand). Ensembl gene ENSG00000111885.
Subcellular location: Golgi apparatus membrane
Subcellular location (Human Protein Atlas): Golgi apparatus
Pathways (Reactome):
Metabolism of proteins: Progressive trimming of alpha-1,2-linked mannose residues from Man9/8/7GlcNAc2 to produce Man5GlcNAc2
Vesicle-mediated transport: Intra-Golgi traffic
Gene Ontology:
Molecular function: mannosyl-oligosaccharide 1,2-alpha-mannosidase activity; protein binding; calcium ion binding; mannosidase activity
Biological process: ERAD pathway; mannose trimming involved in glycoprotein ERAD pathway; protein targeting to ER; Golgi apparatus N-glycan mannose trimming; carbohydrate metabolic process
Cellular component: cytoplasmic vesicle; endoplasmic reticulum-Golgi intermediate compartment; extracellular exosome; Golgi apparatus; membrane; endoplasmic reticulum; Golgi membrane
Genetic constraint (gnomAD): Loss-of-function variants: 16 observed, 47.47 expected, observed/expected ratio (o/e) 0.34, 90% interval 0.23 to 0.51. The upper end of that interval is the gene's LOEUF score, 0.51, which puts it in group 2 of 6, group 1 being the genes least tolerant of losing a copy. Missense variants: 613 observed, 634.97 expected, observed/expected ratio (o/e) 0.97, 90% interval 0.9 to 1.03. Synonymous variants: 309 observed, 264.37 expected, observed/expected ratio (o/e) 1.17, 90% interval 1.06 to 1.28.
Homologues: Orthologues: chimpanzee MAN1A1 (99% identical), macaque MAN1A1 (99% identical), dog MAN1A1 (92% identical), rat Man1a1 (91% identical), mouse Man1a (91% identical), pig MAN1A1 (89% identical), tropical clawed frog man1a1 (71% identical), guinea pig MAN1A1 (70% identical), zebrafish man1a1 (69% identical), Drosophila melanogaster alpha-Man-Ia (45% identical), Caenorhabditis elegans mans-2 (39% identical), Drosophila melanogaster alpha-Man-Ic (31% identical), and 2 more. Paralogues in human: MAN1A2 (61% identical), MAN1C1 (51% identical), MAN1B1 (30% identical), EDEM3 (24% identical), EDEM1 (22% identical), EDEM2 (22% identical).
Diseases named in the same sentence as MAN1A1 in open-access papers:
MAN1A1 is named in the same sentence as 28 diseases in open-access papers, as found by Europe PMC text mining. Sharing a sentence is not in itself a finding about the gene and the disease. The quoted sentences say what the papers report.
breast carcinoma (12 papers, 2009 to 2025). "Dysregulation of MAN1A1 has been shown to be associated with the tumor progression in various types of cancers including breast cancer, ovarian cancer, cholangiocarcinoma, and liver cancer." (PMID 35480887, 2022). "Reduced MAN1A1 expression has previously been associated with reduced survival in breast cancer patients." (PMID 34884649, 2021). "We recently showed a favourable prognostic role of α-mannosidase MAN1A1 in breast cancer mainly caused by alteration of certain adhesion molecules." (PMID 31659304, 2019). "Strikingly, MAN1A1 seems to play opposite roles in metastasis of breast and ovarian cancer: High MAN1A1 expression is associated with less metastasis to lymph nodes as well as brain, lung and bone in breast cancer, whereas it correlates with more distant metastasis in OvCa." (PMID 31659304, 2019). "A previous study on the clinical samples of breast cancer patients showed that the patients who had low levels of MAN1A1 were more likely to have higher tumor metastasis and shorter disease-free survival." (PMID 35216622, 2022). "MAN1A1 silencing or use of the mannosidase inhibitor kifunensine to reduce MAN1A1 expression significantly increases the adhesion of breast cancer cells to endothelial cells." (PMID 35216622, 2022). "Similar to breast cancer, western blot analysis of ovarian tumour tissue generally detects not only the expected 72 kDa band of MAN1A1, but also one or two bands of around 60 kDa." (PMID 31659304, 2019). "Notably, diminished MAN1A1 levels correlate with impaired cell–cell adhesion and unfavorable prognosis in breast carcinoma, whereas its upregulation portends adverse outcomes in hepatocellular and ovarian carcinomas, underscoring context-specific functions." (PMID 40524207, 2025). "HOXD10 and MAN1A1 show an up-regulated gene expression in breast cancer." (PMID 21533145, 2011). "Moreover, high expression of MAN1A1 was correlated with a better outcome of breast cancer patients." (PMID 29915392, 2018).
ovarian carcinoma (5 papers, 2019 to 2025). A malignant neoplasm originating from the surface ovarian epithelium. "Our study demonstrates the unfavourable prognostic role of MAN1A1 in ovarian cancer, probably caused by an altered ability of spheroid formation, and the strong influence of this glycosylation enzyme on the prognostic impact of ALCAM." (PMID 31659304, 2019). "Here, high MAN1A1 levels in tumors were associated with shorter overall survival (OS) and recurrence-free survival (RFS) in ovarian cancer patients." (PMID 39432076, 2024). "MAN1A1 protein expression was detected and compared in benign cystadenomas, borderline tumours and primary or recurrent ovarian carcinomas." (PMID 31659304, 2019). "We analysed the protein expression of MAN1A1 in ovarian cancer (n = 204) using western blot and studied the impact of MAN1A1 itself and of MAN1A1-related glycosylation on the prognostic relevance of two adhesion molecules." (PMID 31659304, 2019). "In conclusion, the results of our present study show an oncogenic role of the Golgi mannosidase MAN1A1 in ovarian cancer, where MAN1A1 expression levels significantly affects RFS and OAS." (PMID 31659304, 2019). "Functional consequences of mannosidase inhibition using kifunensine and MAN1A1 knock out were investigated in ovarian cancer cells in vitro." (PMID 31659304, 2019). "Additionally, the suppression of MAN1A1 by kifunensine in ovarian cancer and breast cancer cells results in the cancer cells being more adhesive to endothelial vascular cells and more aggressive." (PMID 34680335, 2021). "Our results show a MAN1A1-dependent spheroid-formation ability in ovarian cancer cells." (PMID 31659304, 2019). "A recent study has shown that ALCAM expression has a connection with the survival of patients with ovarian cancer, and this connection is dependent on the status of a mannosidase MAN1A1 (Mannosidase Alpha Class 1A Member 1)." (PMID 34680335, 2021).
cholangiocarcinoma (3 papers, 2018 to 2023). A carcinoma that arises from the intrahepatic biliary tree (intrahepatic cholangiocarcinoma) or from the junction, or adjacent to the junction, of the right and left hepatic ducts (hilar cholangiocarcinoma). "Extended high-mannose N-glycans promote metastasis of cholangiocarcinoma in mice membrane proteins via down-regulation of MAN1A1, as shown in MAN1A1-overexpressing KKU-213AL5 cells, while M6, M9, and A3F structures may be associated with tumor progression in human cholangiocarcinoma." (PMID 36766693, 2023).
glioma (3 papers, 2022 to 2024). A benign or malignant brain and spinal cord tumor that arises from glial cells (astrocytes, oligodendrocytes, ependymal cells). "At this stage of the glycosylation process, a marker carbohydrate signature already appears in gliomas due to the altered expression of α1,2-mannosidase MAN1A1." (PMID 39728102, 2024). "Here, it is demonstrated that lower expression of MAN1A1 in glioma stem cell (GSC) resulted in the formation of high‐mannose type N‐glycan on CD133." (PMID 35798319, 2022). "Recently, MAN1A1 (MAN1C1 paralogue) was reported to be downregulated in CD133 + glioma stem cells, suggesting that high-mannose type N-glycan could be an enrichment signal for proneural GSC45." (PMID 39333557, 2024). "Reduced expression of MAN1A1 in glioma stem cells leads to the synthesis of high-mannose N-glycan on the CD133 glycoprotein, which is required for the CD133-DNMT1 interaction, which mediates the maintenance of glioma cells in the stemness state, enhancing drug resistance and tumorigenesis." (PMID 39728102, 2024).
hepatocellular carcinoma (2 papers, 2018 to 2021). A malignant tumor that arises from hepatocytes. "Overexpression of MAN1A1 in a transgenic zebrafish model promoted the development of steatosis, inflammation and hepatocellular carcinoma formation, and also induced the overexpression of MM9, a metalloprotease that seems to be strongly involved in liver fibrosis resolution." (PMID 34441435, 2021). "Lower expression of MAN1A1 in HCCLM3, MHCC97H, and MHCC97L, the metastatic hepatoma cells than Hep3B, the non-metastatic hepatoma cells was reported." (PMID 29915392, 2018).
liver cancer (2 papers, 2018 to 2022). An epithelial or non-epithelial malignant neoplasm that arises from the liver. "The correlation between MAN1A1 expression and metastasis has been reported in liver cancer." (PMID 29915392, 2018).
prostate carcinoma (2 papers, 2019 to 2021). A carcinoma that arises from epithelial cells of the prostate gland. "This suggests that decreased expression of MAN1A1 may be associated with increased prostate cancer aggressiveness and could be a novel marker for identifying a p-EMT phenotype in patient tumors." (PMID 34884649, 2021). "In our study, Ualcan online database analysis showed increased promoter methylation of MAN1A1 in prostate cancer patients compared to healthy controls and in metastatic prostate cancer patients compared to non-metastatic prostate cancer patients." (PMID 34884649, 2021). "We observed significant hypermethylation in 4 of the 10 target genes (MAN1A1, EPB41, HSD17B13, and MYOM2) in primary prostate cancer patient tumors (n = 503) compared to normal prostatic samples (n = 50) (p ≤ 0.05)." (PMID 34884649, 2021).
cervical cancer (1 paper, 2018). A primary or metastatic malignant neoplasm involving the cervix. "It has been shown in melanoma, liver, breast and cervical cancers that aberrant expression of MAN1A1 is associated with the status of methylation at promoter region." (PMID 29915392, 2018).
chronic kidney disease (1 paper, 2025). Impairment of the renal function secondary to chronic kidney damage persisting for three or more months. "While no other studies have linked MAN1A1 to CKD, in knockout mice the MANA1B gene, which is closely related to MAN1A1, has shown an increased severity of acute and chronic kidney disease." (PMID 40004202, 2025).
cystadenoma (1 paper, 2019). A benign or borderline cystic epithelial neoplasm arising from the glandular epithelium. "Interestingly, this smaller MAN1A1 variant is mainly found in non-invasive tumours like cystadenomas and LMP tumours, whereas in carcinomas, the 72 kDa protein predominates and in the OvCa cell lines, only the larger variant is detectable." (PMID 31659304, 2019).
Hypertension (1 paper, 2017). The presence of chronic increased pressure in the systemic arterial system. "Three detected genes were recognized by previous studies, and the other 5 loci/genes (MAN1A1, LMO3, NPAP1/SNRPN, DNAL4, and RNA5SP455/KRT8P5) were novel findings, which had no strong main effect on hypertension and could not be easily identified by single-locus genome-wide studies." (PMID 28642868, 2017).
metastatic prostate carcinoma (1 paper, 2021). A carcinoma that arises from the prostate gland and has spread to other anatomic sites. "Expression of MAN1A1 was also observed to be significantly decreased in metastatic prostate cancer patients (n = 42) relative to non-metastatic prostate cancer patients (n = 44) (p ≤ 0.05)." (PMID 34884649, 2021).
cancer (15 papers, 2012 to 2025). A tumor composed of atypical neoplastic, often pleomorphic cells that invade other tissues. "Additionally, increased expression of oligomannoses in cancer has been linked to reduced expression or activity of α1,2-mannosidases, such as MAN1A1, MAN1A2, and MAN1C1." (PMID 40430030, 2025). "Golgi mannosidases are necessary for the maturation of complex N-glycans, and among this group of enzymes, MAN1A1 seems to play a major role in cancer cells." (PMID 31659304, 2019). "For correlation analysis between MAN1A1 expression and clinical/histological parameters all primary carcinomas were divided into two groups of equal size with MAN1A1 (72 kDa) expression below or above median." (PMID 31659304, 2019). "Our results showed that the MAN1A1 protein level was elevated in the patients with OSA, suggesting that this protein alteration may be linked to the increased risk of cancer development in OSA patients." (PMID 35480887, 2022). "The regulation of MAN1A1 in cancer, however, is still unclear." (PMID 29915392, 2018). "Additionally, a recent study has highlighted a link between OGT and the glycosidase MAN1A1 (Mannosidase alpha class 1A) in cancer cells." (PMID 30400201, 2018). "We found that MAN1A1 and MAN1C1 were significantly downregulated in cancer tissues compared to the healthy urothelium." (PMID 40430030, 2025). "In addition, we found that MAN1A1 and MAN2C1 are downregulated in most cancer types, whereas B4GALT1 and B4GALT3–5 are upregulated in most cancer types." (PMID 41093273, 2025). "MAN1A1, the enzyme responsible for the trimming of high-mannose structures in the ER, is a target gene of FOXO3, elucidating the mechanism by which OGT indirectly controls N-glycosylation found at the surface of cancer cells." (PMID 30400201, 2018).
tumor (13 papers, 2012 to 2025). "In contrast, the fact that inhibition of α-mannosidases and especially loss of MAN1A1 impaired the formation of tumour cell aggregates is in line with the clinical data." (PMID 31659304, 2019). "The analysis of the transposon integration sites identified several candidate genes, of which Man1a1, Pkp4, Rab10, Rasa1, Trps1, Vps26a, Xpnpep3 and Znf326 accelerated tumor growth, whereas the silencing of R3hcc1l reduced tumor growth." (PMID 36497409, 2022). "MAN1A1 was strongly expressed and consistently detected around 72 kDa as expected in all tumours (mean relative expression 376%; range 1.1–2898%)." (PMID 31659304, 2019). "Further, MAN1A1 inhibition, using the α-mannosidase inhibitor kifunensine, or MAN1A1 k.o. leads to an impaired tumour cell aggregation." (PMID 31659304, 2019). "In multivariate analysis including the most important prognostic parameters, FIGO stage and residual tumour after surgery, MAN1A1 expression (72 kDa, 60 kDa or combined) lost its prognostic significance." (PMID 31659304, 2019). "Patients with high MAN1A1 expression in tumours showed significantly shorter RFS than those with low-MAN1A1 levels." (PMID 31659304, 2019). "Surprisingly, the opposite result was found in tumours with low-MAN1A1 protein levels (probably leading to higher amounts of high-mannose N-glycans), where high ALCAM levels were rather associated with a better prognosis." (PMID 31659304, 2019). "In spheroid-formation assays, mannosidase inhibition and especially MAN1A1 knock out led to strong reduction of tumour cell aggregation." (PMID 31659304, 2019). "Then, separate survival analysis was performed in tumours with high and low-MAN1A1 expression." (PMID 31659304, 2019). "This stratification led to interesting results regarding the prognostic impact of ALCAM expression: In tumours with high MAN1A1 expression (probably leading to high amounts of complex N-glycans), high ALCAM protein expression was significantly associated with a shorter OAS and RFS." (PMID 31659304, 2019). "Next, we aimed to clarify whether the expression level of MAN1A1 in tumours could impact the prognostic value of ALCAM and ICAM-1." (PMID 31659304, 2019). "Specifically, we observed that genes participating in the N-glycosylation pathway such as MAN1A1, MGAT1, FUT8, and B4GALT3 were significantly upregulated in neoplasia when compared with healthy subjects." (PMID 40087977, 2025). "LGALS1, B4GALT6, and GALNT11 were upregulated and MGAT5, MAN1A1, MANBA, LUM, GALNT1 and 7, HAPLN3, and ST6GALNAC5 were downregulated in Fra-2 cl 1 select primary tumours, while MGAT4A was upregulated." (PMID 34693476, 2022). "In multivariate Cox regression analysis including clinical stage and residual tumour after surgery, ALCAM lost its prognostic significance in groups with high or low-MAN1A1 expression." (PMID 31659304, 2019). "In both groups (Fra-2 cl 1 and cl 2), some interesting genes could be identified, e.g., in the Fra-2 cl 1 primary tumours LGALS1, ADRM1, and CTTN, which were upregulated and LUM (Lumican), MAN1A1, and SPARC, which were significantly downregulated." (PMID 34693476, 2022). "Further evaluating the microarray data of the scid and the select group, we observed that many genes which are crucial for glycosylation show an altered expression: for example, MAN1A1, MAN2A1, and GALNT 5 and 7 were downregulated in Fra-2 cl 1 scid primary tumours, whereas MGAT4A was upregulated." (PMID 34693476, 2022). "Yet, this finding does not correspond to the favourable characteristics of low-MAN1A1 in tumours and suggests a minor impact of this feature on OvCa progression." (PMID 31659304, 2019). "There were also genes that are of insignificant expression in tumor cells that increase in expression in KO cells, e.g. THBS3, IL2RG, SPRR3, TGM2, HMOX1 and TMEM62 or are lower in expression in tumor cells and significantly decreased in KO cells such as MAN1A1, CES1, STCBP6, SIVA1 and TMEM40." (PMID 31797958, 2019).
tumor (continued). "In addition, optimal debulking results with no macroscopically visible residual tumour were achieved significantly less frequently in cases with high MAN1A1 expression." (PMID 31659304, 2019).
infection (1 paper, 2020). The state of being infected such as from the introduction of a foreign agent such as serum, vaccine, antigenic substance or organism. "We observed that these genes did not change expression in non-CF ALI cultures upon infection with RV; ST8SIA4 (3.6-fold, p = 0.14); ST6GALNAC2 (−1.3-fold, p = 0.09); MAN1A1 (5.4-fold; p = 0.08); B3GNT8 (1-fold, p = 0.28)." (PMID 32765492, 2020).
MAN1A1 also shares sentences with these, for which no sentence is quoted: benign breast tumor (1 paper); bladder cancer (1); COVID-19 (1); gastric adenocarcinoma (1); kidney transplant (1); liver fibrosis (1); lung adenocarcinoma (1); melanoma (1); ovarian tumours (1); pancreatic insufficiency (1); steatosis (1); type 1 diabetes (1); viral infections (1).